KIF26A (kinesin family member 26A)
Description:
Atypical kinesin that plays a key role in enteric neuron development. Acts by repressing a cell growth signaling pathway in the enteric nervous system development, possibly via its interaction with GRB2 that prevents GRB2-binding to SHC, thereby attenating the GDNF-Ret signaling (By similarity). Binds to microtubules but lacks microtubule-based motility due to the absence of ATPase activity (By similarity). Plays a critical role in cerebral cortical development. It probably acts as a microtubule stabilizer that regulates neurite growth and radial migration of cortical excitatory neurons.
Synonyms: KIAA1236; DKFZP434N178; CDCBM11
Tractability: Antibody: the Human Protein Atlas places it where antibodies can reach. PROTAC: ubiquitination databases record sites on it.
Gene: Protein-coding gene on chromosome 14 (104,136,454 to 104,180,894, forward strand). Ensembl gene ENSG00000066735.
Subcellular location: Cytoplasm, cytoskeleton
Subcellular location (Human Protein Atlas): Flagellar centriole; Plasma membrane; Connecting piece; Cytosol; Nucleoplasm
Pathways (Reactome):
Hemostasis: Kinesins
Immune System: MHC class II antigen presentation
Vesicle-mediated transport: COPI-dependent Golgi-to-ER retrograde traffic
Gene Ontology:
Molecular function: protein binding; ATP hydrolysis activity; microtubule binding; microtubule motor activity; ATP binding
Biological process: cerebral cortex development; regulation of neuron migration; regulation of neuron projection development; enteric nervous system development; microtubule-based movement; negative regulation of signal transduction; regulation of cell growth by extracellular stimulus; system development
Cellular component: cytosol; cytoskeleton
Genetic constraint (gnomAD): Loss-of-function variants: 77 observed, 87.35 expected, observed/expected ratio (o/e) 0.88, 90% interval 0.73 to 1.07. The synonymous counts are far from expectation, so gnomAD's model fits this gene poorly and the ratio says little. Missense variants: 2,976 observed, 2,261.3 expected, observed/expected ratio (o/e) 1.32, 90% interval 1.28 to 1.36. Synonymous variants: 1,442 observed, 1,025.8 expected, observed/expected ratio (o/e) 1.41, 90% interval 1.35 to 1.47.
Gene-disease validity (ClinGen):
ClinGen rates the evidence that KIF26A causes each of these diseases.
complex cortical dysplasia with other brain malformations (autosomal recessive): Strong.
Homologues: Orthologues: chimpanzee KIF26A (99% identical), macaque KIF26A (96% identical), dog KIF26A (79% identical), pig KIF26A (79% identical), mouse Kif26a (78% identical), rat Kif26a (76% identical), guinea pig KIF26A (76% identical), tropical clawed frog kif26a (53% identical), zebrafish kif26ab (50% identical), zebrafish kif26aa (45% identical). Paralogues in human: KIF26B (43% identical), KIF14 (11% identical), KIF1A (11% identical), KIF13B (11% identical), KIF1B (11% identical), KIF13A (11% identical), KIF16B (11% identical), KIF1C (10% identical), KIF21A (10% identical), KIF7 (10% identical), KIF27 (10% identical), KIF21B (10% identical), and 29 more.
Diseases named in the same sentence as KIF26A in open-access papers:
KIF26A is named in the same sentence as 29 diseases in open-access papers, as found by Europe PMC text mining. Sharing a sentence is not in itself a finding about the gene and the disease. The quoted sentences say what the papers report.
breast carcinoma (6 papers, 2020 to 2024). "Kif26a has been shown to promote cell proliferation and G0/G1 phase cell cycle progression in breast cancer cells." (PMID 39273313, 2024). "Elevated E2F1 levels activate cell cycle progression and KIF26A expression, thereby promoting the proliferation of breast cancer cells." (PMID 37965271, 2023). "Our results showed that in breast cancer tissues, elevated KIF26A expression was significantly correlated with lymph node metastasis." (PMID 33505901, 2020). "qRT-PCR and immunohistochemistry were conducted to explore KIF26A expression and functional contribution to breast cancer development." (PMID 33505901, 2020). "The aim of this study was to investigate the role of KIF26A in breast cancer." (PMID 33505901, 2020). "We demonstrated that KIF26A could promote proliferation and G0/G1 phase cell cycle progression in breast cancer cells." (PMID 33505901, 2020). "KIF26A could promote proliferation and G0/G1 phase cell cycle progression in breast cancer cells." (PMID 33505901, 2020). "The present study demonstrated that KIF26A, directly upregulated by E2F1, promoted cell proliferation and cell cycle progression via CDK–RB–E2Fs feedback loop in breast cancer." (PMID 33505901, 2020). "We demonstrated that E2F1 induces KIF26A transcription and promotes cell cycle progression via the CDK–RB–E2Fs feedback loop in breast cancer." (PMID 33505901, 2020). "Notably, KIF26A was included in both OS and PFS model, which belongs to kinesin superfamily and is reported as an oncogenic marker for breast cancer and pancreatic ductal carcinoma." (PMID 32883226, 2020).
Brain Malformations (2 papers, 2022 to 2025). "Here, we show that biallelic variants in human KIF26A are associated with a spectrum of congenital brain malformations." (PMID 36228617, 2022). "We report a patient cohort with biallelic loss-of-function variants in KIF26A, exhibiting a spectrum of congenital brain malformations." (PMID 36228617, 2022).
gastric cancer (2 papers, 2023 to 2024). A primary or metastatic malignant neoplasm involving the stomach. "A recent study reported that low expression of KIF26A had a positive correlation with distal metastasis and poor survival in patients with gastric cancer via regulating the focal-adhesion pathway and repressing the occurrence of epithelial-to-mesenchymal transition." (PMID 36837615, 2023).
Hydrocephalus (2 papers, 2022 to 2025). Hydrocephalus is an active distension of the ventricular system of the brain resulting from inadequate passage of CSF from its point of production within the cerebral ventricles to its point of absorption into the systemic circulation. "D01 from Family D (PMG_14800) was diagnosed with polymicrogyria and hydrocephalus, with inherited compound heterozygous variants in KIF26A: c.2845C>T, p.Pro949Ser, and c.4676C>T, p.Ala1559Val." (PMID 36228617, 2022).
megacolon (2 papers, 2022 to 2025). "In mice, Kif26a knockout (KO) results in megacolon, enteric neuronal hyperplasia, and impaired neurite outgrowth." (PMID 39305096, 2025). "Among previous cases, two homozygous truncating KIF26A variants were associated with megacolon resembling Hirschsprung's disease without aganglionosis." (PMID 39305096, 2025). "Kif26a knockout (KO) mice exhibit megacolon, enteric neuronal hyperplasia and defective neurite outgrowth, but the role of KIF26A in the central nervous system has not yet been characterized." (PMID 36228617, 2022).
migraine (2 papers, 2020 to 2023). "Remaining genes differentially methylated in migraine were kinesin family member 26A (KIF26A), dedicator of cytokinesis 6 (DOCK6), and complement factor D (CFD) that were reported to associate with various aspects of the aging process." (PMID 37199585, 2023).
polymicrogyria (2 papers, 2022 to 2023). A developmental brain abnormality characterized by an excessive amount of small convolutions on the surface of the brain and cognitive dysfunction. "In addition to detecting pathogenic variants in genes previously linked to polymicrogyria (eg, ADGRG1/GPR56, SCN3A, TUBB2B), we discovered 6 genes linked to polymicrogyria for the first time (QRICH1, TMEM161B, PANX1, KIF26A, SCN2A, and MAN2C1)." (PMID 37486637, 2023).
cerebral palsy (1 paper, 2025). A group of disorders affecting the development of movement and posture, often accompanied by disturbances of sensation, perception, cognition, and behavior. "However, we observed severe spastic quadriplegic cerebral palsy (CP) with epilepsy in patient #3, suggesting that the neurological involvement in KIF26A patients may be heterogeneous." (PMID 39305096, 2025).
colon cancer (1 paper, 2020). "KIF26A and ZIC2 gene expression, with which shRNA efficacy displayed significant scores, were found to correlate with the survival rate from colon cancer patient data." (PMID 33114107, 2020). "Furthermore, KIF26A and ZIC2 gene expression, with which shRNA efficacy displayed significant scores, were found to correlate with the survival rate from colon cancer patient data." (PMID 33114107, 2020).
colorectal cancer (1 paper, 2026). A primary or metastatic malignant neoplasm that affects the colon or rectum. "Furthermore, lower KIF26A expression was associated with colorectal cancer (CRC) progression, migration, and invasion." (PMID 42003912, 2026). "In this study, we demonstrated that kinesin family member 26A (KIF26A) is downregulated in chemoradioresistant colorectal cancers, as revealed by transcriptomic analyses of colorectal cancer tissues and cell lines." (PMID 42003912, 2026). "Reduced KIF26A levels predicted diminished responsiveness to chemoradiotherapy and unfavorable outcomes in patients with colorectal cancer." (PMID 42003912, 2026). "Thus, our research elucidates the function of KIF26A in the NHEJ repair process and indicates that combining HDACi with chemoradiotherapy may serve as a promising therapeutic modality for colorectal cancer." (PMID 42003912, 2026).
Hirschsprung disease (1 paper, 2025). Hirschsprung disease (HSCR) is a congenital intestinal motility disorder that is characterized by signs of intestinal obstruction due to the presence of an aganglionic segment of variable extent in the terminal part of the colon. "In this study, we describe three novel unrelated patients harboring biallelic variants in KIF26A and presenting with neurodevelopmental disorder, congenital megacolon with features of Hirschsprung's disease, and brain defects." (PMID 39305096, 2025).
lung carcinoma (1 paper, 2024). "This includes genes involved in cancer progression such as Kif26a, Acer2, Serpine1, Nr1d2, Efnb2 as well as Chst11, which have all previously been shown to be deregulated in various forms of cancer, including lung cancer." (PMID 39273313, 2024).
neuroblastoma (1 paper, 2022). Neuroblastoma (NB) is the most common solid, extracranial childhood tumor. "In human neuroblastoma cell line SHSY5Y, overexpression of WT KIF26A, but not variant KIF26As, stabilizes microtubules, making them resistant to depolymerization induced by Nocodazole treatment, a small molecule commonly used for this purpose." (PMID 36228617, 2022).
schizencephaly (1 paper, 2022). "Overall, these five families associate biallelic KIF26A mutations with corpus callosum defects, ventricular abnormalities, cortical malformations on the polymicrogyria/schizencephaly spectrum and additional variable brain and systemic abnormalities." (PMID 36228617, 2022).
tumor (8 papers, 2018 to 2025). "KIF26A restrained progression of many tumor-types, although its impact on HCC remains unclear." (PMID 38433242, 2024). "The intensive expression of KIF26A and ALDH1A2 on smooth muscle cells suggests their potential involvement in tumor progression." (PMID 39440060, 2024). "Immunocytochemistry showed KIF13A and KIF26A mainly localized in cytoplasm and membrane, and KIF13B and KIF4A mainly concentrated at membrane and nuclear that significantly upregulated in tumor samples." (PMID 36837615, 2023). "Kinesin-11 family: KIF26A and KIF26B appear to have opposing roles in tumor progression." (PMID 38433242, 2024). "Interestingly but notably, two members (KIF26A and KIF26B) of this subfamily have opposing effects on tumor progression." (PMID 38433242, 2024). "Finally, KIF4A, KIF13A, KIF13B, and KIF26A were identified from the HPA database, and all these KIFs differentially expressed between normal and tumor samples." (PMID 36837615, 2023). "Among the overexpressed genes, PTGDS (13.761-fold) had the highest log2 fold change in tumor versus non-tumor tissues, followed by TNFRSF18 (13.387-fold), glial fibrillary acidic protein (GFAP) (12.296-fold), BARHL1 (12.175-fold), and KIF26A (11.719-fold)." (PMID 30195786, 2018).
cancer (3 papers, 2020 to 2024). A tumor composed of atypical neoplastic, often pleomorphic cells that invade other tissues. "These analyses identified several cancer-related genes, including Kif26a, Acer2, Serpine1, Nr1d2, Efnb2, and Chst11, to be affected by ECS exposure." (PMID 39273313, 2024). "GO analysis and GSEA revealed disruption of MAPK, E2F and MYC pathways, echoing two very recent studies also reporting KIF26A’s involvement in MYC and E2F pathways in cancer." (PMID 36228617, 2022). "However, the role of KIF26A, a homologous family member of KIF26B, in cancer remains unknown." (PMID 33505901, 2020).
neurodevelopmental disorder (2 papers, 2022 to 2026). A behavioral and cognitive disorder with onset during the developmental period that involves impaired or aberrant development of intellectual, motor, or social functions. "Kif26a and Kif26b encode a family of unconventional kinesins with emerging roles in neurodevelopment, and mutations in both genes have been implicated in a spectrum of neurodevelopmental disorders." (PMID 42239235, 2026). "Although many kinesins have been associated with neurodevelopmental disorders, KIF26A is unique because it does not function as a molecular motor, but instead modulates signal transduction via direct binding to FAK and GRB2." (PMID 36228617, 2022).
KIF26A also shares sentences with these, for which no sentence is quoted: brain disease (1 paper); Cerebral atrophy (1); clear cell renal cell carcinoma (1); congenital brain malformations (1); developmental and epileptic encephalopathy (1); epilepsy (1); glioma (1); hepatocellular carcinoma (1); Insulin resistance (1); intestinal pseudo-obstruction (1); pancreatic ductal carcinoma (1); Ververi-Brady syndrome (1).